ABL1 (ABL proto-oncogene 1, non-receptor tyrosine kinase)
Diseases named in the same sentence as ABL1 in open-access papers (continued):
Sharing a sentence is not in itself a finding about the gene and the disease.
kidney tumors (1 paper, 2016). "FH-deficiency may activate the proto-oncogene ABL1 in kidney tumors, which may upregulate aerobic glycolysis via the mTOR/HIF1α pathway, being a promising target marker." (PMID 27556703, 2016).
leiomyosarcoma (1 paper, 2017). An uncommon, aggressive malignant smooth muscle neoplasm, usually occurring in post-menopausal women. "Interestingly, two leiomyosarcoma cell lines (SK-LMS, SK-UT1) did not express ABL1 at detectable levels." (PMID 27965460, 2017).
leukopenia (1 paper, 2022). "Leukopenia influenced BCR-ABL1 measurements because samples with leukopenia did not achieve enough ABL1 copies of ≥ 10,000 for DMR and ≥ 32,000 for MR4.5." (PMID 35967571, 2022).
lymph node metastasis (1 paper, 2017). "Among these, ABL1 K690del was identified in a NPC liver metastasis (HKNPC-091) and a lymph node metastasis (P-10-27817)." (PMID 28098136, 2017).
microcephaly (1 paper, 2021). A congenital or acquired developmental disorder in which the circumference of the head is smaller than normal for the person's age and sex. "This case series of six new patients with germline heterozygous ABL1 missense variants further delineates the phenotypic spectrum of this condition and recognises microcephaly as a common finding." (PMID 33223528, 2021).
nonalcoholic fatty liver disease (1 paper, 2021). "Surprisingly, ABL1 was also associated with nonalcoholic fatty liver disease (P=5.96e − 08)." (PMID 34484330, 2021). "Functional network analysis revealed that ABL1 plays an important role in mitochondrial activity, ATP metabolism, protein translation and metabolism, various neurological diseases, nonalcoholic fatty liver disease, and notch signaling pathway." (PMID 34484330, 2021).
Noonan syndrome (1 paper, 2017). Noonan Syndrome (NS) is characterized by short stature, typical facial dysmorphism and congenital heart defects. "Four of the proteins are linked to various forms of the Noonan syndrome (CBL, MAP2K1, RAF1 and SOS), 5 to various types of tumors (MAPK1, PRKCQ, ABL1, GRAP2 and RAS) and one to an autoimmune disorder (RASGRP1)." (PMID 28448599, 2017).
ovarian tumour (1 paper, 2013). "Two other candidates that have not previously been tested as RGs in ovarian tumour tissue, ABL1 and CDKN1A, were selected from the commercial gene array." (PMID 24001041, 2013).
overnutrition (1 paper, 2018). An imbalanced nutritional status resulting from excessive intake of nutrients. "The histone H3 lysine 4 methyltransferase, Mll4/Kmt2d, directs overnutrition-induced murine steatosis via its coactivator function for PPARγ2, whereby overnutrition activates Abl1 kinase which phosphorylates PPARγ2, and hence has enhanced interaction with Mll4." (PMID 30283300, 2018).
preeclampsia (1 paper, 2024). Preeclampsia is a hypertensive disorder of pregnancy that is characterized by new-onset hypertension with proteinuria presenting after 20 weeks of gestation, and depending on mild or severe forms may initially present with severe headache, visual disturbances, and hyperreflexia. "A previous study also showed that ABL1 methylation is upregulated in preeclampsia." (PMID 38886689, 2024).
psychological distress (1 paper, 2025). "Excessive ROS production due to psychological distress can activate the ABL proto-oncogene 1 (ABL1), promoting inflammatory pathways and GC progression." (PMID 40641920, 2025).
Sensorineural hearing impairment (1 paper, 2021). A type of hearing impairment in one or both ears related to an abnormal functionality of the cochlear nerve. "Hearing impairment has recently been identified as a common feature of the ABL1 malformation syndrome; four of our cohort exhibit conductive or mixed conductive/sensorineural hearing impairment, which was severe and persistent in one patient." (PMID 33223528, 2021).
squamous cell carcinoma (1 paper, 2025). A carcinoma arising from squamous epithelial cells. "In the first step, we measured YAP, LATS1/2, JNK1/2, ABL1 and MAP4K4 gene expression in the A431 cell line to identify which disturbances in the Hippo pathway and their regulators are present in the standardized squamous cell carcinoma cell line." (PMID 40149574, 2025).
van den Ende-Gupta syndrome (1 paper, 2023). Van den Ende-Gupta syndrome is a very rare syndrome characterized by blepharophimosis, arachnodactyly, joint contractures, and characteristic dysmorphic features. "This is readily seen in the case of ABL1 homozygous loss of function variant that we suggest produces a mirror-image phenotype to ABL1-related Van den Ende Gupta syndrome-like facial and digit dysmorphism caused by de novo gain of function variants." (PMID 37644014, 2023).
vitiligo (1 paper, 2021). Generalized well circumscribed patches of leukoderma that are generally distributed over symmetric body locations and is due to autoimmune destruction of melanocytes. "Among these articulation proteins, previous study had reported that Imatinib (ABL1 inhibitor) induced repigmentation of vitiligo lesions." (PMID 34603063, 2021).
cancer (380 papers, 2006 to 2026). A tumor composed of atypical neoplastic, often pleomorphic cells that invade other tissues. "For example, how broad ABL1’s involvement in R-loop-associated DNA repair varies across different cancer types, and if there are other substrates or cofactors that modulate ABL1’s activity in this context." (PMID 40918650, 2025). "NGS studies have confirmed the role of mutations in cancer-related genes other than BCR::ABL1 mutations in drug resistance and treatment failure." (PMID 37762109, 2023). "Approximately 85% to 100% of the patients in BC with BCR::ABL1 kinase domain mutations also had cancer gene mutations, including gene fusions and deletions." (PMID 37762109, 2023). "The co-occurrence of BCR::ABL1 kinase domain mutations and cancer gene mutations in a high proportion of resistant patients indicates that we should not consider resistance as either BCR::ABL1-dependent or BCR::ABL1-independent." (PMID 35158889, 2022). "In blast crisis, 85% to 100% of patients with BCR::ABL1 kinase domain mutations also had cancer gene mutations, including gene fusions and deletions." (PMID 35158889, 2022). "In this and our previous study we use mouse models: in the previous study the disease was driven by the proto-oncogene BCR/ABL1, while in this study cancer risk was elevated by deletion of the tumor suppressor ARF." (PMID 29441205, 2018). "Using the left-hand scale bars to judge the impact of each mutation type, ABL1 primarily drives cancer development by kinase-domain point mutations and over-expression." (PMID 27899578, 2017). "IPA analysis of these unique up-regulated genes indicated that some genes were associated with cell transformation during cancer progression (ABL1, TRIO, FOSB, NRCAM, TRIB2 and CDK6) and others with cell survival (e.g., BCL10, BBC3, FGF8, HSPA4 and SOD1)." (PMID 29137349, 2017). "ABL1 has been implicated to be activated and promote phenotypes associated with cancer, by mechanisms including loss of the ABL1 negative regulator FUS1." (PMID 26758680, 2016). "Gain‐of‐function mutations often enhance or confer tumorigenic phenotypes and somatically mutated ABL1 is likely contributing to enhanced survival and/or proliferation of cancer cells through increased activity." (PMID 26758680, 2016). "Better sequencing methods are likely to reveal additional compound mutations in Abl1 and other cancer drug targets." (PMID 24376513, 2013). "Pathogenic roles of ABL1 are further discussed in the ABI1 in cancer section of this review." (PMID 39354505, 2024). "Mutations in mTOR and ABL1 are noteworthy given they are activating in other cancers resulting in increased cell proliferation, and may contribute to cholangiocarcinogenesis in this fashion." (PMID 37095160, 2023). "The impact of cancer-related gene mutations detected at the time of CML diagnosis may vary depending on whether they were acquired before or after BCR::ABL1." (PMID 35932396, 2022). "Clicking on the phrase ‘Haematopoietic & Lymphoid’ will show a breakdown of the cancer disease classifications under this tissue, indicating that ABL1 mutations primarily drive 28% of evaluated Chronic Myeloid Leukaemias, and 32% of Acute Lymphoblastic Leukaemias (in COSMIC v78)." (PMID 27899578, 2017). "Interestingly, recurrent mutations of genes previously reported to be mutated in cancer: ABL1, BUB1B, NCOR1 (each mutated in three tumours), and CARS, HSP90AB1, NCOA1 (each mutated in two tumours) were uniquely found in recurrent/metastatic NPCs (n=33)." (PMID 28098136, 2017). "However, lymphoid gene mutations may also be relevant for lymphoid phenotype BC CML, and BCR::ABL1 mutations frequently co-occur with cancer gene mutations." (PMID 37762109, 2023).
cancer (continued). "However, lymphoid gene mutations may also be relevant for lymphoid phenotype blast crisis CML and BCR::ABL1 mutations frequently co-occur with mutated cancer genes." (PMID 35158889, 2022). "To ensure the enhanced degradation of the ABL1 protein was due to an on-target mechanism, we evaluated whether cancer-derived mutations, including Y87C, F102C, W131G, and F133V 44, that abrogate SPOP binding to substrates would fail to promote ABL1 protein degradation." (PMID 34795215, 2021). "Besides, quercetin could inhibit the activities of many kinases implicated in cancer cell biology, such as ABL1, Aurora-A, -B, -C, CLK1, FLT3, JAK3, and MET." (PMID 31998395, 2019). "We retrieved frozen bone marrow DNA samples for all patients that presented at diagnosis with a WT1/ABL1 level lower than 250 at the three institutions of our comprehensive cancer and research network from 2013 to 2017." (PMID 40227798, 2025). "Our estimates of the duration from the start of BCR::ABL1 clonal expansion to disease presentation fall within ranges from radiobiological studies of cancer incidences in Japanese survivors of the atomic bombs." (PMID 40205062, 2025). "The results of mRNA expression show that ABL-1 genes were significantly increased in all cancer cell lines." (PMID 40872562, 2025). "This uncovered function of ABL1 at sites of R-loops has significant implications for cancer therapy, particularly in cancers where transcriptional dysregulation and DNA repair are intertwined." (PMID 40918650, 2025). "Our new finding that ABL1 is actively recruited to R-loops highlights a crucial role of ABL1 in maintaining genomic stability in cancer cells." (PMID 40918650, 2025). "The identification of ABL1’s role in R-loop-mediated DNA repair adds a significant new dimension to our understanding of ABL1’s function in cancer biology." (PMID 40918650, 2025). "In summary, these experiments showed that RoCK and ROI can be used both in cell lines and patient samples for the detection of both major and minor BCR::ABL1 fusion transcripts in the context of cancer." (PMID 41372142, 2025). "The colony formation in SKOV3 wildtype or MUC16+ and OVCAR8 cells showed that lack of ABL1/SYCP2 expression or SYCP2 phosphorylation activity mediated by ABL1 would largely reduce the cancer cell survival." (PMID 40918650, 2025). "By targeting ABL1’s role in R-loop-dependent DNA repair, particularly through the use of TKIs such as imatinib or dasatinib, we can disrupt this pathway and render cancer cells more vulnerable to chemotherapy." (PMID 40918650, 2025). "Compared to primary cancer, ABL1(0.3% vs 3.0%, p=0.007) and FGFR1 (7.1% vs 13.1%, p=0.016) were more likely to be observed in R/M sites." (PMID 40182039, 2025). "For example, in the DLX4 gene module, connections among DLX4, the known cancer gene ABL1, and four candidate AML genes (SP1, FYN, GRB2, and SMAD2) co-occurred in multiple patients." (PMID 39013885, 2024). "Recent studies have demonstrated the overexpression or dysregulated activation of ABL1 in cancers such as lung, breast, colon, and renal carcinoma, indicative of its potential role in solid tumors." (PMID 39060421, 2024). "Another study showed that a multi-target compound against tubulin assembly and ABL1 significantly inhibited the growth of a panel of cancer cell lines." (PMID 38424554, 2024). "Interaction between ABI1 and ABL1 also affects centrosome organization during mitosis, a commonly dysregulated process in cancer." (PMID 39354505, 2024). "Although no noteworthy cluster was found in upregulated genes unique to 9S1R-NulloPT treated cancer, Abl-1 and Shc-1 formed the center node of a small cluster." (PMID 37461536, 2023). "In CML, the constitutively active BCR::ABL1 kinase drives leukaemic proliferation through stimulation of several key cell survival pathways frequently activated in cancer." (PMID 37591854, 2023).
cancer (continued). "The oncogenic kinasesyielded a substantially different linear motif when compared to ABL1.Kinase set enrichment analysis with human pY-sites that have highlinear motif scores well-recalled BCR-ABL driven cancer cell linesfrom human phospho-proteome data sets." (PMID 37053475, 2023). "Our knowledge of how the BCR::ABL1 gene and resulting protein drive cancer cell progression and survival through complex processes within the cell which promote cell growth and switch off normal cell death pathways." (PMID 38550948, 2023). "It was reported that ABL1 promotes cancer cell growth, survival, adhesion, and migration depending on the cellular context." (PMID 36193491, 2022). "Potential cancer target activity was also reflected by the docking in the current study, with a glide score of −10.2 against Tyrosine-protein kinase ABL1 for one of the parazoanthines." (PMID 35049897, 2021). "For example nocodazol, a colchicine binding site agent was found to simultaneously inhibit various cancer-related kinases, including ABL1, c-KIT, BRAF, MEK1 (MAP2K1), MEK2 (MAP2K2), and MET." (PMID 33671106, 2021). "Nevertheless, BCR/ABL1 inhibition with imatinib (Gleevec), a tyrosine kinase inhibitor, resulting in ceasing disease progression, was the first success of cancer targeted therapy, changing CML from a fatal disorder into a chronic disease." (PMID 33671579, 2021). "The association of these proteins with DEK-NUP214 was proposed to promote activation of several cancer associated pathways, such as AKT/mTOR, Src family kinase (SFK), ABL1, and c-MYC pathways." (PMID 32664447, 2020). "Both tested compounds were effective in blocking ABL1 kinase and lowering the 2-hydroxyglutarate in cancer cells." (PMID 32110969, 2020). "We focused our validation experiments on three major kinases involved in cancer: the tyrosine kinase ABL1, the mitogen‐activated protein kinase (MAPK) member ERK2, and one of the four p38 MAPKs, MAPK14." (PMID 33021050, 2020). "Targeted deep-sequencing analysis of the tumors at sacrifice revealed that BA-targeted xenografted tumors analyzed 6 weeks after AdV injection were composed of non-edited (94%) or partially-edited (one locus; 3% of BCR or ABL1) cancer cells." (PMID 33033246, 2020). "Validation experiments were performed on three major kinases involved in cancer biology: ABL1, MAPK1/ERK2, and MAPK14/p38α." (PMID 33021050, 2020). "The evolution of a relatively stable pool of cancer stem cells is modelled as a stochastic process, with the growth of cells expressing a tumourigenic protein (here, Abl1) and any emerging mutants determined principally by the drugs used in the therapy." (PMID 31138173, 2019). "Other novel, highly scoring gene pair predictions that included cancer associated genes included PARP1 with PBRM1, BRCA2, ARID1A and APC as well as PIK3CA with MAP2K1, ABL1 and EGFR." (PMID 30995217, 2019). "Depending on cellular context and cancer type, the proliferative effects of ABL1 can be exerted by controlling upregulation of c‐myc or cyclin D1." (PMID 26758680, 2016). "It was recently reported that quercetin inhibits a panel of kinases including NEK4, NEK9, and ABL1 in cancer cells." (PMID 27602754, 2016). "Due to the expression of ABL1 in all cancer cell lines investigated in this study, the relevance of this kinase in mediating the pharmacologic activity of HVS cannot be discounted." (PMID 27086914, 2016). "Top-ranking kinases such as AKT1, CHEK2, and ABL1 regulate core cellular processes of growth and proliferation, and are well-studied cancer drivers according to the CancerGenes database." (PMID 25611800, 2015). "SATB1 is a global chromatin organizer that directly regulates the expression of ERRB2, MMP2, ABL1 and E-cadherin to act as a key regulator of cancer development." (PMID 24675979, 2014).